STAT3 (signal transducer and activator of transcription 3)
Diseases named in the same sentence as STAT3 in open-access papers (continued):
Sharing a sentence is not in itself a finding about the gene and the disease.
Sepsis (continued). "The overexpression of some miRNAs was induced by the synergistic effect of STAT3 and C/EBPβ, which activated miR-21 and miR-181b promoters after sepsis initiation." (PMID 31413755, 2019). "miR-375 also regulated the function and miR-21 expression of those MDSCs through targeting JAK2 and further impairing STAT3 in the mice with sepsis." (PMID 31413755, 2019). "This is the case with miR-223, which plays a protective role in both autoimmune hepatitis (by regulating NLRP3 and caspase-1) and in sepsis (by inhibiting Sema3A and Stat3)." (PMID 31533317, 2019). "With regard to the impact of POMC knockdown on hepatic GNG in sepsis rats, we next measured expression of STAT3 and key enzymes involved in GNG via Western blot or quantitive PCR analysis." (PMID 29285858, 2018). "In experimental studies, inhibition of JAK2 with AG490 or STAT3 with rapamycin attenuated organ damage and severe sepsis mortality." (PMID 28182798, 2017). "Collectively, current observations indicate that inhibition of EGFR protects kidney injury and is associated, at least in part, with significant inhibition of ERK1/2 and STAT3 signaling in mice with sepsis." (PMID 29207668, 2017). "The liver also maintains immune homeostasis in other organs, with an important role for hepatocyte signal transducer and activator of transcription 3 (STAT3) during sepsis and pneumonia." (PMID 27751165, 2016). "STAT3-mediated protection in this model of polymicrobial sepsis was attributed to the serum amyloid A and CXCL1-dependent mobilization of myeloid-derived suppressor cells." (PMID 27751165, 2016). "In this study we show that these receptors are also potent regulators of immune homeostasis during sepsis, showing a link between thyroid hormone signalling and STAT3 and ERK activation." (PMID 27484112, 2016). "Hepatic STAT3 activity was necessary to prevent an excessive systemic inflammatory response and attenuate lethality after cecal ligation and puncture-induced sepsis." (PMID 27751165, 2016). "Concomitant upregulation of G-CSFR on HSCs during sepsis, a known inducer of STAT3 phosphorylation during emergency myelopoiesis, is probably responsible for the majority of STAT3 activation." (PMID 26272069, 2015). "As a result, the miR-223 targets (i.e., Sema3A and Stat3) were down-regulated, leading to the inhibition of inflammatory response in macrophages and attenuation of cardiomyocyte death during sepsis." (PMID 26348153, 2015). "In a sepsis model, STAT3 phosphorylation has been reported as an important step prior to NFκB activation in nicotine treated macrophages." (PMID 25296021, 2014). "There also are reports that ERK1/2 and STAT3 as upstream regulator participating in the activation of NF-κB signaling pathway in sepsis." (PMID 23781122, 2013). "We have also shown that both the phosphorylated and total protein expression levels of STAT3 in spleen neutrophils of plg-/- mice were markedly lower than those in WT mice after induction of sepsis." (PMID 21931850, 2011). "In the sepsis model, levels of total and phosphorylated STAT3 in WT mice increased significantly upon induction of sepsis." (PMID 21931850, 2011). "In our studies, we found that levels of total and phosphorylated STAT3 remained largely unchanged in plg-/- mice undergoing sepsis, which is in contrast to the dramatic increased STAT3 activation in WT mice undergoing sepsis." (PMID 21931850, 2011). "Thus, effective suppression of the JAK2/STAT3 pathway appears to have substantial therapeutic value in sepsis and diseases with comparable pathogenesis." (PMID 39955435, 2025). "The WB experiment revealed a significant increase in Stat3 expression in HK2 cells after sepsis." (PMID 40181843, 2025). "One study has demonstrated that mitochondrial STAT3 exacerbates LPS-induced sepsis." (PMID 40177399, 2025). "Notably, higher expression of Stat3 was observed in HK2 cells post-sepsis through Rela, potentially inducing ferroptosis and a worse prognosis." (PMID 40181843, 2025).
Sepsis (continued). "Candidate sepsis genes were identified in this study: Rela and Stat3." (PMID 40181843, 2025). "Inhibition of JAK3 and STAT3 has been shown to reduce the overexpression of endothelial adhesion molecules, thereby mitigating pathological conditions such as vascular paralysis, coagulation dysfunction, and multi-organ failure (MOF) associated with sepsis." (PMID 41041277, 2025). "However, we did not observe that Trim21 promoted ubiquitin-mediated degradation of Stat3 in renal tubular cells during sepsis-induced AKI." (PMID 40344718, 2025). "Moreover, agonist activation of STAT3 profoundly potentiated the PDPNhi PM subset generation and alleviated sepsis severity in mice." (PMID 39903516, 2025). "For instance, IL-6 activates STAT3 that initially provides anti-inflammatory protection in sepsis, but its prolonged activation may contribute to immune paralysis." (PMID 41041277, 2025). "For instance, in lipopolysaccharide-induced sepsis, signal transducer and activator of transcription 3 (STAT3) expression was found to be upregulated, which inhibited the ubiquitination of CPT1A produced by macrophages, stabilizing CPT1A expression under the mediation of USP50." (PMID 41219902, 2025). "Other studies concluded that STAT3 plays a significant role in developing and progressing sepsis." (PMID 40177399, 2025). "In addition, SOCS3, a suppressor of the JAK2/STAT3 pathway, exhibited higher expression in the sepsis and TCZ16 groups, as anticipated, in response to high inflammation." (PMID 39955435, 2025). "Accumulating evidence suggests that STAT3 activation is a critical mediator of various types of acute and chronic lung injury, such as sepsis-induced acute lung injury, ischemia-reperfusion injury (IRI), BPD, and fibrosis, by promoting apoptosis, oxidative stress, and inflammation." (PMID 40969747, 2025). "Recent research has emphasized the crucial role of STAT3 in sepsis pathophysiology." (PMID 38245687, 2024). "Therefore, we propose that MASP-1 triggers traumatic sepsis by activating the IL6/JAK/STAT3 signaling pathways and promoting CD8 T-cell depletion after traumatic injury." (PMID 38384415, 2024). "Suppressing SOCS1 may promotes glycolysis and pro-inflammatory responses in sepsis murine bone marrow cells via the STAT3/HIF-1α axis This implies that EV-miRNA may promote the glycolysis of septic macrophages." (PMID 39744123, 2024). "To explore whether STAT3 inhibition can improve the immune status in late sepsis by affecting PMN-MDSCs, we first evaluated whether the inhibition of STAT3 phosphorylation with Stattic could affect the differentiation and function of PMN-MDSCs in vitro." (PMID 38385073, 2024). "Additionally, the inhibition of STAT3 activation also improved the immunosuppressive state and survival in late sepsis by negatively affecting PMN-MDSCs." (PMID 38385073, 2024). "Finally, further in vitro and in vivo experiments should be conducted in future studies to elucidate the regulatory mechanisms and functional roles of MASP-1, CD8 T cells, and IL6/JAK/STAT3 signaling pathways in trauma and sepsis." (PMID 38384415, 2024). "The aims of this study were to investigate whether TLR4/IKKα-mediated NF-κB and JAK2/STAT3 pathways were involved in XBJ's cardio-protection during sepsis and the mechanisms." (PMID 37650558, 2023). "Some questions remain to be answered, such as whether MCL shows a similar effect on Stat3 as ACT001 in sepsis management." (PMID 38094883, 2023). "In addition, many studies have shown that targeting STAT3 has a broad application prospect in treating sepsis." (PMID 36817458, 2023). "It has been shown that the STAT3 pathway is closely associated with inflammatory diseases including sepsis, and inhibition of the JAK-STAT3 signaling pathway is expected to improve the prognosis of sepsis." (PMID 36737780, 2023).
Sepsis (continued). "Previous studies have shown that inhibition of STAT3 phosphorylation levels during the hyperinflammatory phase of sepsis and increasing STAT3 phosphorylation levels during the immunosuppressive phase both improve pathogen clearance and improve healing in septic rats." (PMID 36737780, 2023). "STAT3 was further up-regulated during the transition from healthy to sepsis induction." (PMID 36817458, 2023). "The key role of STAT3 signalling in the pro-inflammatory response in septic cardiomyopathy has been illustrated in previous studies; STAT3 may contribute to the development of systemic inflammation in sepsis." (PMID 36160853, 2022). "Likewise, phosphorylation of STAT3 was markedly augmented at 24 h after the onset of sepsis, in combination with simultaneous induction of IFNGR2." (PMID 35832091, 2022). "Our study results further suggest that the pharmacological blockade of mitochondrial STAT3 function by curcumin could be a promising treatment strategy for sepsis, metabolic disorders, and other inflammatory diseases." (PMID 34976224, 2022). "The activation of the STAT3 signaling pathway is closely related to the occurrence of a variety of inflammatory diseases, such as ulcerative colitis, rheumatoid arthritis, and sepsis, especially in the sepsis-mediated inflammatory reaction." (PMID 35799194, 2022). "Thus, in this study, we aimed to investigate the protective effect of EA pre-treatment against sepsis cardiomyopathy and the potential role of calpain-2/STAT3 signalling in process ofinflammation and apoptosis." (PMID 36160853, 2022). "In sepsis, the role of calpain-2-regulated STAT3 in cardio-protective mechanism of electroacupuncture remains unclear." (PMID 36160853, 2022). "To determine whether STAT3 localizes in mitochondria in humans, we extracted the mitochondrial fraction of phagocytes from sepsis patients and healthy volunteers and performed SDS-PAGE." (PMID 34976224, 2022). "Some studies have shown that STAT3 activation contributes to organ protection in sepsis." (PMID 35733865, 2022). "Importantly, we confirmed that electroacupuncture combined with STAT3 inhibition was more effective in protecting sepsis cardiomyopathy than electroacupuncture alone." (PMID 36160853, 2022). "Therefore, in this study, we utilized inducible mitochondrial STAT3 knock-in mice and discovered that following treatment with LPS, mitochondrial STAT3 exacerbated sepsis along with an increase in FAO via the stabilization of CPT1a." (PMID 34976224, 2022). "Studies have shown a critical role of STAT3 in the pathophysiology of sepsis." (PMID 35957694, 2022). "Therefore, downregulating the JAK1/STAT3 signaling pathways was a potential avenue of ZJF in reversing lung injury induced by sepsis." (PMID 33506010, 2021). "CXCR5 may act via p38MAPK/NF-κB/STAT3 signaling to inhibit hippocampal autophagy during sepsis and thereby contribute to cognitive dysfunction." (PMID 34711216, 2021). "Because of this, SIRT1 knockout sepsis mice appear to have active NF-κB, STAT3, and extracellular signal-regulated kinase (ERK) 1/2, thus providing the lungs with an unusually strong inflammatory signal by upregulating a range of pro-inflammatory mediators, including IL-ip, IL-6, and TNF-α." (PMID 33693011, 2021). "Together, FUNDC1-dependent MAMs is important in LPS-induced sepsis and IL-6/STAT3 inhibitor might improve cardiac dysfunction through regulating the FUNDC1-dependent MAMs formation." (PMID 35118141, 2021). "Moreover, IL22 has been reported to relieve sepsis-induced liver injury via activating the JAK/STAT3 signaling pathway, suggesting that IL22-producing ILC3s exert regulatory functions on damaged tissues other than the intestine." (PMID 33513946, 2021). "Additionally, in the clinical study, the western blot analysis of the proteins HIF-1α and STAT3 showed that the expression of protein STAT3 was significantly reduced in the late phase of sepsis compared with the primary phase." (PMID 32089644, 2020).
Sepsis (continued). "Interestingly, with the coimmunoprecipitation assay, results showed that proteins HIF-1α and STAT3 coregulated at the transcriptional level in the immune process of sepsis." (PMID 32089644, 2020). "However, the pathogenetic role, if any, of the STAT3 pathway in the development of key organ dysfunction in sepsis remains to be explored." (PMID 32943679, 2020). "Alternatively, the use of STAT3 inhibitors, such as stattic, in sepsis treatment might unmask IL-6-mediated but STAT3-independent unexpected harmful reactions." (PMID 32943679, 2020). "Moreover, we also found that the HIF-1α was activated in hypoxic conditions during the primary phase in sepsis, which then coactivated the signal transducer and activator of transcription 3 (STAT3) to engage in the inflammatory process." (PMID 32089644, 2020). "Additionally, the proteins HIF-1α and STAT3 were coregulated at transcriptional levels during the inflammatory responses of sepsis." (PMID 32089644, 2020). "Finally, STAT3 decoy ODN administration minimized the development of sepsis-driven major end-organ injury and led to a significant survival advantage in mice after CLP." (PMID 32943679, 2020). "The impact of ODN decoy to STAT3 on mortality in this rodent sepsis model appears to be more pronounced when compared with those of other transcription factors, such as NF-κB and AP-1, which are major participants in modulating the transcription of the immunoregulatory mediators." (PMID 32943679, 2020). "Whether STAT3 decoy administration can improve survival of mice with CLP-induced sepsis was addressed." (PMID 32943679, 2020). "In line with the view that STAT3 decoy ODN operates to trap activated STAT3, which dimerizes and translocates into the nucleus, in the cytoplasm, its transfection was found to be without effect on STAT3 phosphorylation associated with CLP-induced sepsis." (PMID 32943679, 2020). "Our results thus indicate that HMGB1 may be one of the potential target molecules for the therapeutic strategy using STAT3 decoy ODNs in sepsis treatment." (PMID 32943679, 2020). "In this study, we demonstrate that STAT3, one of the STAT family members that has been implicated to be a key transcription factor in both immunity and inflammatory pathways, is greatly activated in major end-organ tissues of mice with CLP-induced sepsis." (PMID 32943679, 2020). "Moreover, in the clinical study, the programmed cell death-ligand 1 (PD-L1) was overexpressed in monocytes in the late phase of sepsis, while the expression of proteins HIF-1α and STAT3 was decreased in the late phase of sepsis." (PMID 32089644, 2020). "Although previous report has proved that IL-6 is the main factor stimulating the expression of hepcidin through the STAT3 signaling pathway in patients with septicemia and burns, the high level of hepcidin mRNA is also observed in IL-6-deficient mice with chronic inflammation." (PMID 31814801, 2019). "Although previous study has proved that IL-6 is the main factor stimulating the expression of hepcidin through the STAT3 signaling pathway in patients with septicemia and burns and that the high level of hepcidin mRNA is also observed in IL-6-deficient mice with chronic inflammation." (PMID 31814801, 2019). "Sema3A and Stat3 are considered fundamental activators of the sepsis process." (PMID 31533317, 2019). "Lowering the expression of another miRNA, miR-223, was associated with an increase in neutrophil infiltration and myocardial dysfunction in a sepsis patient via activation of STAT3/IL6 and Sema3, indicating that the presence of the miR-223 prevents this influx and lowers inflammation." (PMID 30523422, 2018). "During polymicrobial sepsis, miR-223 contained inside EVs contributes to the regulation of two proteins, semaphorin-3A (Sema3A) and signal transducer and activator of transcription 3 (Stat3), which are involved in apoptosis." (PMID 28224125, 2017).
Sepsis (continued). "In this work we demonstrate that these receptors control hepatic cytokine production and signalling during sepsis in vivo and that the thyroid hormone directly antagonizes IL-6 signalling in cultured hepatocarcinoma cells and macrophages, leading to reduced STAT3 transcriptional activity." (PMID 27484112, 2016). "Nonetheless, we believe that our study may suggest that therapeutic effects of MSCs on sepsis are, at least in part, dependent on the axis of miR-223-Sema3A/Stat3 mediated by exosomes." (PMID 26348153, 2015). "α7 nAChR agonists control systemic inflammation in sepsis by inhibiting the JAK2/STAT3 pathway which plays an important role in transducing a multitude of inflammatory signals; it has been considered as a therapeutic target for suppressing inflammatory process." (PMID 23840548, 2013). "Thus, one possible explanation is that plasmin is important in mediating complement activation, which subsequently activates the STAT3 signaling pathway and contributes to the different phenotypes observed in plg-/- and WT mice during infection and sepsis." (PMID 21931850, 2011). "Furthermore, deposition of the active complement mediator C5a on the surface of neutrophils as well as activation of STAT3 is impaired in plg-/- mice after induction of sepsis." (PMID 21931850, 2011). "Phospho-Tyr705-STAT3 in the brain was increased 4 hr after either ip or icv LPS administration, confirming that STAT3 is activated in the brain after sepsis." (PMID 19284588, 2009). "We found that IRF7 might be stimulated by the IFN-β/JAK1/STAT3 pathway in polymicrobial sepsis." (PMID 41212050, 2025). "Particularly, it was shown to suppress STAT3 activation in a variety of inflammation and injury models, including neuroinflammation, intestinal mucosal injury induced by ischemia-reperfusion damage, as well as heart, kidney, lung, and liver injury induced by sepsis and ischemia-reperfusion." (PMID 39042159, 2025). "Given that the STAT3 agonist colivelin could increase the percentage of the induced PDPNhi PM subset in WT septic mice, we sought to determine its therapeutic potential for the treatment of sepsis." (PMID 39903516, 2025). "Moreover, EX-527 notably detracted from melatonin’s protective stance against sepsis-induced liver damage, hyperglycemia, and STAT3 deactivation, proffering prospects for melatonin’s approach in treating sepsis-induced liver damage through SIRT1-mediated STAT3 pathways." (PMID 38690282, 2024). "Similarly, exosomes derived from BMSCs, acting as carriers for delivering miR-125b-5p into macrophages, suppress the expression of signal transducer and activator of transcription 3 (STAT3), thereby halting macrophage pyroptosis and alleviating sepsis-associated ALI." (PMID 39840035, 2024). "This difference in infiltrated immune cell type could be explained by the different signaling between CLP and LPS model, as LPS majorly acts via Toll-like receptor (TLR) pathways, while CLP-induced sepsis activates inflammation via STAT3 and cytokine expression." (PMID 39726718, 2024). "Therefore, resisting apoptosis by inhibiting the activation of TLR4/NF-κB and JAK2/STAT3 signaling pathways may have clinical benefits for patients who suffer from sepsis induced myocardial dysfunction." (PMID 37650558, 2023). "In addition, the JAK2/STAT3 pathway plays a role in the onset and progression of sepsis." (PMID 37650558, 2023). "However, other studies have demonstrated that the suppression of STAT3 activity may ameliorate the organ inflammatory responses and display remarkable protective effects in sepsis." (PMID 35733865, 2022). "To confirm the hypothesis, we examined STAT3 localization in phagocytes from sepsis patients." (PMID 34976224, 2022).